MPO (myeloperoxidase)
Diseases named in the same sentence as MPO in open-access papers (continued):
Sharing a sentence is not in itself a finding about the gene and the disease.
colitis (continued). "The administration of HnAb inhibited significantly the MPO expression as compared to vehicle-treated DSS-induced colitis mice." (PMID 33193406, 2020). "Next, we evaluated the immunoreactivity of MPO to assess the distribution of neutrophils in the colonic mucosa of colitis mice seven days after initiation of DSS treatment." (PMID 33192516, 2020). "The results suggest that sinapic acid markedly reduces leukocyte (neutrophil and macrophage) infiltration and decreases the colonic MPO levels to ameliorate inflammatory conditions in the colon tissues of DSS-induced colitis mice." (PMID 33312339, 2020). "Regarding neutrophilic activity, all DSS-induced colitis groups showed increased MPO activity in colon tissue lysate." (PMID 33092149, 2020). "SA treatment also significantly reduced the histological infiltration of inflammatory cells and decreased myeloperoxidase (MPO) activity in the colons of colitis mice." (PMID 33312339, 2020). "On day five, colitis indices of tissue specimens were evaluated and levels of biochemical markers including myeloperoxidase (MPO) and malondialdehyde (MDA) were determined." (PMID 32995327, 2020). "In a murine 2,4,6-trinitrobenzene sulfonic acid (TNBS)-induced colitis model, vidofludimus treatment reduced the levels of MPO in colonic tissue, thus implicating similar effects on immune cell hyperactivation in other relevant clinical situations." (PMID 33291455, 2020). "In colitic mice, the formulation significantly reduced TNF-α mRNA (50%) and protein (45%) expression and ameliorated colitis symptoms reflected by the DAI, loss of body weight, colon length, MPO activity and histopathology." (PMID 32545207, 2020). "Oral gavage of Rd or protopanaxtriol also suppressed EC-induced colitis: they inhibited myeloperoxidase activity, NF-κB activation, and NF-κB+/CD11c+ cell population in the colon." (PMID 32224881, 2020). "Accordingly, the administration of the C. procera methanolic extract significantly reduced MPO activity levels during DSS-induced colitis, which indicates that fewer neutrophils infiltrated the mucosa and submucosa compared with the DSS group." (PMID 32377161, 2020). "MPO activity was reduced distinctly in all treatment groups compared to the untreated colitis control and three of four chitosan and 5-ASA combinations even led to a significant reduction compared to 5-ASA alone." (PMID 33138176, 2020). "Stainings for Adamts1, Adamts5, and Bmp1 showed similar distribution patterns as the MPO-staining, indicating that these proteases are contributed not by the colon epithelium, but by invading neutrophils/monocytes on colitis induction." (PMID 32160911, 2020). "In the present study, the activity of MPO was significantly elevated in the colonic tissues of experimental colitis (p < 0.05) compared to the control rats." (PMID 33061833, 2020). "Infiltration of neutrophils plays a key role in pathogenesis of DSS-induced colitis, and increased MPO activity represents neutrophil accumulation." (PMID 32038240, 2019). "Further, another study reported that Astragalus reduced NF-κB DNA phosphorylation activity and decreased the levels of TNF-α, IL-6, and MPO activity in the setting of colitis." (PMID 30610157, 2019). "Colonic and pulmonary myeloperoxidase activity was severely augmented upon colitis induction indicating a conspicuous recruitment of granulocytes within tissues." (PMID 31297055, 2019). "Both medications induced a significant reduction in the activity of MPO and the intensity of nitric oxide production and malondialdehyde in the gut homogenate of animals with colitis compared to positive control animals." (PMID 31763213, 2019). "Capsazepine significantly decreased the levels of disease activity index (DAI), myeloperoxidase (MPO) activity in DSS-induced colitis." (PMID 30871017, 2019).
colitis (continued). "We have previously shown the anti-inflammatory effect of physical exercise; recreation led to reduced area of lesions and decreased expression of Il-1β (interleukin 1 beta), CXCL1 (C-X-C motif chemokine ligand 1), and MPO in a rat model of colitis." (PMID 31010141, 2019). "It down-regulates leukotriene B4, iNOS production and MPO activity in TNBS model of rat colitis and down-regulated COX-2 expression in catla thymus macrophages." (PMID 31579453, 2019). "In murine model of DSS-induced colitis, the increase in MPO and pro-inflammatory cytokines occurred after the onset of colon inflammation due to physical barrier disruption." (PMID 30430451, 2019). "Different data are consistently affirming that TNBS induced colitis is characterized by an increase of MPO activity, suggesting exacerbation of the colon inflammation." (PMID 31581545, 2019). "All treatments significantly decreased the MPO level in colonic tissues in comparison with AA-colitis group." (PMID 34466462, 2019). "Emulsifiers promote colitis in IL-10-/- mice by increasing inflammatory markers such as fecal lipocalin-2 or myeloperoxidase activity." (PMID 31109097, 2019). "Mice submitted to the TNBS developed colitis, as evidenced by the analysis of the macroscopic lesions and MPO activity that are classical inflammatory parameters assessed to confirm inflammatory reactions." (PMID 31370166, 2019). "The data agree with the study by Pereira, Pereira, Figueiredo, Freitas, Dinis and Almeida who have also found lower levels of MPO and iNOS after treatment of colitis with a blueberry fraction." (PMID 31731626, 2019). "The obtained data indicated that the MPO activity and the malondialdehyde intensity as well as nitric oxide in the colonic homogenate of rats with colitis were signifacntly increased compared to normal rats." (PMID 31763213, 2019). "In a TNBS rat colitis model, Escherichia coli Nissle 1917, at low doses of the strain (107cfu/day), has been demonstrated to reduce the disease activity index, colonic MPO activity, and TNF‐α levels and to increase IL‐10 expression." (PMID 31572604, 2019). "In DSS-induced colitis, large numbers of myeloid cells (Cd11b positive), including macrophages (F4/80 positive) and neutrophils (MPO positive), infiltrated into the mucosa and epithelial layer of the damaged colon." (PMID 31019191, 2019). "MPO, an enzyme in neutrophils, has been shown to be an effective marker for assessing granulocyte infiltration in colon tissue after the induction of colitis." (PMID 31262973, 2019). "Following the induction of colitis, MPO is released from neutrophils, oxidative stress occurs in the body, and the expression of SOD and MPO increases in colon tissue." (PMID 31093294, 2019). "The colitis control group displayed a significant increase in the level of MPO activity as compared with Sham group (P < 0.001)." (PMID 32641944, 2019). "L. acidophilus administration reduced colonic leukotriene B4 (LTB4) production, inducible nitrogen oxide synthase (iNOS) expression and myeloperoxidase (MPO) activity in the TNBS model of rat colitis." (PMID 31035617, 2019). "We also evaluated the production of MPO, an indicator of neutrophil filtration and colitis severity, in the colons of infected mice." (PMID 30842764, 2019). "In comparison with the TNBS group, 5-ASA-ALA significantly reduced the MPO activity in colon homogenate of colitis mice and produced a better result than the positive control." (PMID 32133064, 2019). "Their treatments also alleviated colitis: They inhibited IS-induced colon shortening, myeloperoxidase activity, and macrophage and DC infiltration into the gastrointestinal tract." (PMID 30979031, 2019). "Dizocilpine, particularly with intermediate dose of 1mg/kg significantly improved animal’s weight loss as well as macroscopic and microscopic signs of colitis, reduced colonic levels of IL-1β, IL-6, TNF-α and MPO activity." (PMID 32641944, 2019).
colitis (continued). "In a chronic colitis model, CEC more strongly decreased signs of colitis severity (myeloperoxidase activity and CD3+ immune-cell infiltration) than Nissle." (PMID 31391483, 2019). "These include, but are not limited to, histological analysis with scoring by a pathologist, cytokine expression at the mRNA and protein levels, and other indirect measures of colitis activity such as tissue myeloperoxidase (MPO) analysis." (PMID 32123846, 2019). "Fortunellin ameliorated colitis symptoms, including decreasing macroscopically visible damage, the colon weight-to-length ratio, MPO activity, and intestinal permeability, in the miR-374a negative control group." (PMID 29472916, 2018). "Studies have shown that nicotinamide enhanced the antimicrobial activity of neutrophil, improved tissue damage and reduced the activity of MPO of DSS-induced colitis mice significantly." (PMID 30042683, 2018). "In the murine model of DSS-induced colitis, the increase in MPO and pro-inflammatory cytokines occurred after the disruption to the intestinal barrier, indicating that compromised barrier function results in progression inflammation." (PMID 28528363, 2018). "Rats with DNBS-induced colitis showed a marked increase in colonic MPO levels (56.3 ± 4.9 ng/mg tissue), as compared with control animals (3.2 ± 1.1 ng/mg tissue)." (PMID 30559669, 2018). "As a marker of inflammation in experimental colitis, MPO levels after P28GST curative treatment were evaluated in this study." (PMID 30592734, 2018). "In rats treated with saline after the induction of colitis, myeloperoxidase activity in colonic mucosa was increased almost two-fold 14 days after the induction." (PMID 29865176, 2018). "Pathology and the MPO functional assay suggested that DSS-induced colitis significantly increased the presence of neutrophils in the intestines of CerS6-deficient mice." (PMID 29374263, 2018). "The disease activity index, myeloperoxidase activity, and inflammatory cytokines in the colonic mucosa were evaluated 7 days after dextran sodium sulfate-dependent colitis induction." (PMID 30487665, 2018). "Compared with normal mice, jet-lagged mice were much more sensitive to DSS-induced colitis as evidenced by the inflammation index values (i.e., weight loss, disease activity index (DAI), histopathological score, colon length, and myeloperoxidase (MPO))." (PMID 30315268, 2018). "Here, with oral AD-licoTM administration, there was a substantial disruption of the colonic architectural changes due to DSS and a significant reduction in colonic myeloperoxidase (MPO) activity, a marker of colitis." (PMID 30460097, 2018). "The aims of this study were to investigate the protective efficacy of CAPE in the mouse model of colitis and determine its effect on MPO activity, pro-inflammatory cytokines levels, and intestinal permeability." (PMID 28528363, 2018). "Neutrophils often exert pro-inflammatory functions at sites of inflammation, and a neutrophil-derived protein, myeloperoxidase, is widely used as a marker of colitis severity in IBD." (PMID 30455703, 2018). "MPO is a biomarker of neutrophil infiltration characterizing damage of host tissues with inflammation in human and animal model of colitis." (PMID 30592734, 2018). "Treatment with obestatin given at doses of 4, 8, or 16 nmol/kg reduced the colitis-evoked increase in myeloperoxidase activity in the colonic mucosa." (PMID 29865176, 2018). "Our results show that CAPE is effective in suppressing inflammation-triggered MPO activity and pro-inflammatory cytokines production while enhancing epithelial barrier function in experimental colitis." (PMID 28528363, 2018). "MPO activity of the mice with DSS-induced colitis significantly increased compared with that of the untreated DSS mice (p < 0.01)." (PMID 29495327, 2018). "MPO activity, as an indicator of the severity of colitis, is proportional to the level of neutrophil infiltration in the inflammatory tissue." (PMID 29880739, 2018).
colitis (continued). "Arginine treatment of mice with DSS colitis was shown to reduce mucosal permeability, the number of MPO-positive neutrophils, and expression of proinflammatory cytokines and chemokines and to increase iNOS activity." (PMID 28832517, 2017). "A large amount of evidence indicates that animals subjected to TNBS-induced colitis suffer from diarrhea, weight loss, disorganization of the colon mucosa and sub-mucosa, and significantly increased MDA content, MPO activity, TNF-α and IL-1β." (PMID 28056930, 2017). "The present study demonstrated that baicalein alleviated the severity of TNBS-induced colitis in mice by decreasing the activity of myeloperoxidase (MPO) and the expression of pro-inflammatory mediators." (PMID 29180692, 2017). "A significantly (P < 0.05) increased MPO activity in the DSS-induced colitis was observed compared to the mice in the CON and MR group; this increase was suppressed by the administration of the MR diet (P< 0.05)." (PMID 28562346, 2017). "Seven days after colitis induction, the extent of inflammation in the colon was assessed by measuring neutrophil infiltration (MPO activity), proinflammatory cytokine levels (TNF-α and IL-1β), and inflammation parameters." (PMID 29123119, 2017). "Administration of ghrelin resulted in a statistically significant inhibition of myeloperoxidase activity in the mucosa of pituitary-intact animals with colitis." (PMID 28538694, 2017). "Treatment with ARF, along 8 days after colitis induction, reduced significantly MPO activity and its protein expression in a higher extent than with 5-ASA, indicating a higher anti-inflammatory action." (PMID 28329021, 2017). "In inflamed colon the level of MPO activity [units/mg tissue] was significantly [p<0.05] higher as compared to the non colitis control colon [closed bars]." (PMID 28493993, 2017). "We found that oral administration of DSS in NLRP3−/− mice induced a less severe colitis than WT mice and produced lower levels of MPO and IL-1β in colonic tissues, which suggested the important role of NLRP3 inflammasome in DSS-induced colitis." (PMID 28553294, 2017). "We measured MPO activity in colon tissues of mice with DSS-induced colitis and found the DSS group exhibited high MPO activity." (PMID 28270147, 2017). "IBD98-M treatment also reduced myeloperoxidase activity and the expression levels of cyclooxygenase 2 and tumor necrosis factor-αin the colitis tissue." (PMID 28556814, 2017). "As expected, DSS led to large increases in tissue MPO levels consistent with induction of colitis in the colon of sham and control animals." (PMID 28922370, 2017). "Colitis was characterized by measuring MPO activity, body weight, and colon hypertrophy, and microscopically by H&E and alcian blue staining." (PMID 28493993, 2017). "We have been able to show that orally administered ZnSA at 1.0 × 10−3 mol kg−1 significantly reduces the colitic score (60%) and myeloperoxidase activity (58%) in an acute colitis model (mouse)." (PMID 28425040, 2017). "In the colitis rats, mechanical thresholds at the neurogenic spots over the hind paw were inversely correlated with an increase of MPO activity—an indicator of colitis (Pearson correlation coefficient, −0.914; P = 0.0015)." (PMID 29123119, 2017). "In a study to evaluate the anti-inflammatory and antioxidative effects of EGCG on a DSS-induced murine colitis model by intragastric application, which corresponded to applicable forms for humans, the MPO was tested to assess the leukocyte infiltration." (PMID 28335502, 2017). "DSS-induced colitis is characterized by substantial immune cell infiltration into colon tissue and myeloperoxidase (MPO) is a biomarker for neutrophil or monocyte/macrophage infiltration." (PMID 28270147, 2017). "Improvement of the symptoms of DSS colitis (aggravation of gross symptoms, colon shortening, histopathological changes accompanying tissue damage, and myeloperoxidase activation) was observed with oral administration of WT-NCC2705 alone." (PMID 28179904, 2017).
colitis (continued). "The pathologic injury score and MPO activity in the colitis group were significantly higher than those of the control group." (PMID 29156831, 2017). "Aloperine also attenuated the inflammation of colitis in mouse based on the pathological score and MPO, which is a specific marker of neutrophil infiltration that is often used to assess disease activity in colitis." (PMID 29056830, 2017). "Doxepin after i.p. administration was effective to reduce colitis severity through reduction in the macroscopic and microscopic colonic parameters, MPO activity and cytokines levels." (PMID 28694747, 2017). "The highest myeloperoxidase activity in the mucosa of the colon was observed in hypophysectomized rats with colitis." (PMID 28538694, 2017). "Myeloperoxidase (MPO) activity in the colon was significantly higher in DSS-colitis mice than that in untreated mice (P < 0.05)." (PMID 27893428, 2017). "Compared with DSS group, bergenin (20, 50 mg/kg) and 5-ASA (100 mg/kg) significantly reduced DAI scores and MPO activity in colons of colitis mice." (PMID 29375382, 2017). "Colitis rats also had higher MPO activity (indicating neutrophil infiltration into the damaged tissue), higher pro-inflammatory cytokine levels, including TNF-α, IL-1β, and IL-8." (PMID 29176974, 2017). "The therapeutic efficacy of PCA on experimental colitis was assessed by macroscopic and microscopic damage of the colonic mucosa, body weight change and MPO activity." (PMID 28300788, 2017). "Significantly attenuated levels of inflammatory cytokines TNF-α, MPO, macroscopically visible damage score, and colon weight-to-length ratio were responsible for the resistance to colitis recurrence in Sal B treated group." (PMID 27303297, 2016). "Enhanced colonic tissue levels of myeloperoxidase activity (a neutrophil-rich enzyme) has been reported in various animal models of colitis as well as in IBD patients." (PMID 27997590, 2016). "Treatment with obestatin reduced the colitis-evoked increase in myeloperoxidase activity in the colonic mucosa." (PMID 26798415, 2016). "Neutrophils from Tollip deficient mice subjected to DSS-induced septic colitis exhibited heightened inflammatory responses such as elevated levels CCR5, and increased secretion of MPO." (PMID 27703259, 2016). "Our present study has shown that treatment with ghrelin reduces activity of MPO in rats with colitis." (PMID 27598133, 2016). "Mice of group rSjcystatin-TNBS developed severe inflammation as TNBS-induced colitis of mice at the level of MPO (0.92 ± 0.28 vs 1.45 ± 0.52) U/g, MAO (7.14 ± 0.69 vs 7.83 ± 0.98) and MIO (5.17 ± 0.75 vs 6.17 ± 1.72) 3 days afterwards." (PMID 26728323, 2016). "At 2 weeks after the second course of DSS colitis, we examined colonic mucosa for inflammation by staining colonic sections for MPO, Gr1 (neutrophil marker) or CD68 (macrophage marker) by immunofluorescence staining method." (PMID 26951793, 2016). "Decreased MPO activity illustrated the benefits of alpinetin treatment in the mouse model of DSS-induced colitis." (PMID 27321991, 2016). "As we known, myeloperoxidase activity is an established marker for inflammatory cell (mainly neutrophils) infiltration and activity in murine models of colitis." (PMID 27544348, 2016). "In this study, we have used three parameters to give a comprehensive evaluation of the inflammation of colitis, including pathology score, MPO activity, and FITC permeability." (PMID 27029486, 2016). "Histological, macroscopic colitis scores and tissue myeloperoxidase activity were significantly reduced." (PMID 27418880, 2016). "Other than shorten colon, colitis was also characterized by augmented colonic myeloperoxidase (MPO) activity." (PMID 27488951, 2016). "In rats treated with saline after induction of colitis, 7 days after induction of this inflammation, myeloperoxidase activity in colonic mucosa was increased by 318%." (PMID 26798415, 2016).